LCN2 (lipocalin 2)
Diseases named in the same sentence as LCN2 in open-access papers (continued):
Sharing a sentence is not in itself a finding about the gene and the disease.
cancer (continued). "Surprisingly, lipocalin-2 expression has been shown to be increased in many types of cancer in recent years, including esophageal, pancreas, ovarian, breast, lung, and gastric cancer." (PMID 33542838, 2021). "On the basis of abnormal expression in some cancers, the iron-binding protein Lipocalin-2 (LCN2) may play a substantial role in metastasis." (PMID 34988012, 2021). "The research indicates that LCN2 could be a novel biomarker to evaluate cancer surveillance related to disease duration of developing UC into UCAC." (PMID 35111677, 2021). "Moreover, dysregulation of LCN2 at the protein and mRNA level in IBC has been observed and associated with cancer progression." (PMID 34445288, 2021). "The role of lipocalin 2 (Lcn2) in cancer is controversial in this sense some studies referred to its function in cancer promotion and others emphasized the anticancer ability of this molecule especially in suppression of invasion, angiogenesis, and metastasis in different types of cancers." (PMID 34249257, 2021). "Consecutively, cancer cell expansion is supported by the LCN2/SLC22A17 system." (PMID 34988012, 2021). "We hypothesize that cancer cells secrete Lcn-2 in its iron-free form, which might be rapidly taken up to diminish stress-induced cellular death." (PMID 34069743, 2021). "Therefore, the role of LCN2 in anti-metastasis is remarkably divergent not only among the different cancer types but also between various cell lines in the same cancer." (PMID 34202288, 2021). "Although debate continues regarding the pro- or anti-neoplastic role of LCN2 in a variety of cancers, our findings suggested that LCN2 may be a promising anti-proliferative and anti-metastatic target for treating GBM in the future." (PMID 34062746, 2021). "LCN2 is expressed in various cells, including cancer cells, and its expressing pattern varies." (PMID 34359830, 2021). "To figure out whether LCN2 expression correlates with cancer, we evaluated LCN2 expression in different tumors and adjacent normal tissues." (PMID 33425761, 2020). "Whether LCN-2 also has to be included as an iron-trafficking protein in the context of cancer, still needs detailed analysis of its mechanism of action and its iron-transporting as well as iron-donating function." (PMID 31772326, 2020). "In addition, Lcn2 is capable of interacting with matrix metalloproteinases via the formation of complexes, and then participating in the cancer cell invasion process." (PMID 32154171, 2020). "Therefore, the results indicated that LCN2 expression was tightly correlated with the extent of immune infiltration in cancers." (PMID 33425761, 2020). "Currently, LCN2 has received considerable attention as both a promising biomarker and vital mediator of various human cancers, but the relevance of LCN2 function with the tumorigenesis is still unknown." (PMID 33425761, 2020). "LCN2 might be considered as a novel target for cancer therapy since they showed upregulation in multiple cancers and correlated with worse prognosis." (PMID 33425761, 2020). "The identification of specific tumor receptors of each cancer type in which LCN2 is overexpressed could also improve the specificity of the CRISPR/Cas9-containing nanocarriers." (PMID 32575507, 2020). "Given the resemblance of wound healing to cancer development, it is tempting to speculate that lipocalin-2 derived from TAM or neutrophils stimulates cancer cell growth by an iron-dependent mechanism." (PMID 33679721, 2020). "Besides, we investigated the genomic alterations, expression pattern, and survival analysis of LCN2 in pan-cancer across numerous databases, including cBioPortal and GEPIA database." (PMID 33425761, 2020). "This hypothesis is supported by evidence showing the production of antioxidant enzymes such as heme oxygenase (HO-1) and superoxide dismutases (SO-1,2) in LCN2-overexpressing cancer cells." (PMID 32575507, 2020). "LCN2 expression levels are clearly modulated in many types of cancers." (PMID 32575507, 2020).
cancer (continued). "The study of LCN2 as a therapeutic target in cancer is still in the early stages of development." (PMID 32575507, 2020). "LCN2 is an acute-phase protein with emerging roles in the brain and in cancer." (PMID 33171886, 2020). "Finally, we describe the approaches to targeting LCN2 for cancer treatment that are currently under investigation, such as gene editing, interference RNA, and antibody-based therapy." (PMID 32575507, 2020). "Lipocalin-2 can be expressed by other cell types including cancer cells." (PMID 33679721, 2020). "Association between LCN2 expression and TMB varied markedly among cancer types." (PMID 33425761, 2020). "The production of LCN2 is often increased in disease conditions, and it is known to be involved in sterile inflammation, wound-healing and tissue remodelling, fibrosis, kidney failure, neurodegeneration and cancer progression." (PMID 33292361, 2020). "Because current treatment options for aggressive cancers are limited, LCN2 may be a promising therapeutic target against these cancer subtypes." (PMID 32575507, 2020). "Targeting LCN2 has been shown to be beneficial in different mouse cancer models." (PMID 32575507, 2020). "Due to the fact that LCN2 has a potential role as a sensitive indicator in saliva, it might represent an important new target or biomarker for cancer diagnosis." (PMID 33425761, 2020). "For the same reason, the prognostic value of LCN2 may vary depending on confounding factors, but its increased level among numerous cancers makes LCN2 a promising biomarker for this disease." (PMID 32575507, 2020). "However, the therapeutic efficacy and safety of LCN2-antibody-based therapy will need to be evaluated in clinical trials, most likely in combination with current therapies for each cancer type being targeted." (PMID 32575507, 2020). "Thus, it is crucial to investigate ferroptosis by manipulating the LCN2 expression levels in cancer cells before proposing this molecular pathway as a target for therapy." (PMID 32575507, 2020). "Next, we further assessed the prognostic value of LCN2 for pan-cancer (OS and RFS) in GEPIA." (PMID 33425761, 2020). "In several cancer types and in line with a perturbed iron regulation, LCN2 plays an important role in oncogenesis and cancer progression and may serve as a disease biomarker." (PMID 30636005, 2019). "The role of LCN2 in promoting the tumorigenesis of other cancers is also well known." (PMID 31151292, 2019). "Several studies have demonstrated that apo-Lcn2 induces apoptosis in Lcn2-R expressing cells, whereas holo-Lcn2 is anti-apoptotic and may even promote cell proliferation, e.g. in cancer cells." (PMID 30404645, 2018). "Furthermore, NGAL forms a complex with MMP-9 like Lcn2 and increases its stability which is crucial in cancer cell invasion as well as response to chemotherapy." (PMID 30591630, 2018). "LCN2 may contribute to both iron uptake and iron release by several cell types including cancer cells and TAMs." (PMID 30534534, 2018). "Expression of LCN2 is also associated with epithelial-mesenchymal transition (EMT), invasion, progression and metastatic spread of many types of cancer cells including those of breast, cholangiocellular, intestinal or prostate origin but model-specific differences exist." (PMID 30534534, 2018). "Lcn2 can also be released into the extracellular matrix and promote iron internalization and sequestration through known receptors such as megalin, contributing to cancer cell survival and metastasis." (PMID 30591630, 2018). "Given that TIMP1 and LCN2 may be elevated in other cancer types, they are best suited as part of a panel for subjects at increased risk such as those with a history of FPC." (PMID 30241369, 2018). "Sporadic evidence for this hypothesis has been obtained from cancer studies, but systemic studies investigating the role of apo- versus holo-Lcn2 in renal epithelial regeneration following various insults would be desirable." (PMID 30404645, 2018).
cancer (continued). "Lipocalin 2 has been identified as a stress protein that is released in a variety of other sterile inflammatory conditions such as adipose obesity-related inflammation and cancer." (PMID 28088789, 2017). "Mechanistically, Lcn-2 production was connected to S1P release from apoptotic cancer cells." (PMID 28979267, 2017). "Pathway analysis and animal results indicate that LCN2 may promote cancer cell migration and invasion through EMT." (PMID 26840566, 2016). "Recently, it has been reported that LCN2 is involved in cancer progression." (PMID 27912767, 2016). "As LCN2 expression has been reported by several types of cancer and is induced in hypoxic states, it is reasonable to argue that iron sequestration by LCN2 might promote cell survival and tumorigenesis." (PMID 27136530, 2016). "Increased LCN2 expression has been described in variety of cancers." (PMID 25940797, 2015). "LCN2 is associated with EMT, and promotes cancer cell migration." (PMID 25940797, 2015). "A recent study showed that LCN-2 is involved in the regulation of inflammation and cancer." (PMID 23393601, 2013). "Several studies have identified LCN2 as an upregulated gene in cancer." (PMID 23056397, 2012). "In malignant tumors, studies have indicated that LCN2 may be involved in epithelial-mesenchymal transition (EMT)." (PMID 22559235, 2012). "Increased expression of lipocalin 2 (LCN2) has been observed in several cancers." (PMID 22559235, 2012). "Soon after the discovery of lipocalin-2 as a constituent of neutrophil specific granules, lipocalin-2 was found to be highly up-regulated in epithelial cells at sites of inflammation and to be highly expressed in some cancers." (PMID 22737251, 2012). "This may also be the case with lipocalin-2 indicating that the effect of Lcn2 on cancer development is dependent on the genetic setting of the individual organism." (PMID 22737251, 2012). "In parallel, a link between Lipocalin 2 and cancer has also been reported." (PMID 21649922, 2011). "Taken together, these findings suggest that ER stress in cancer cells may be the primary triggering event for Lipocalin 2 activation via the Grp78/AKT/NF-κB axis." (PMID 21649922, 2011). "Some studies about the roles of lipocalin 2 in cancer progression supported our findings." (PMID 19077278, 2008). "This enhancement suggested that lipocalin 2 might provide some advantage to the cancer cells growing in the complex cellular environment of the host tissues." (PMID 19077278, 2008). "However, cancer cells hijack the innate immune functions of LCN2 within the TME." (PMID 41303420, 2025). "However, in TNBC metastasis, changes in basal LCN2 levels during interactions with the TME or with other cancer cells might be more important than its absolute expression level." (PMID 41303420, 2025). "Thus, more evidence is warranted to elucidate the relationship between LCN2 and cancer." (PMID 38035773, 2024). "Besides its effects on macrophage polarization, we hypothesize that the C5a-C5aR pathway may upregulate LCN2 by activating endoplasmic reticulum (ER) stress, thereby enhancing iron transport to cancer cells." (PMID 39850877, 2024). "And there was an experiment showing that adipocytokines were involved in the carcinogenesis process, and an adipocytokine, LCN-2, has been reported to have the ability to destroy the extracellular matrix, which may lead to cancer progression and metastatic spread." (PMID 39717768, 2024). "This could serve as a foundation for targeting Lcn-2 to induce cancer cell apoptosis." (PMID 37958332, 2023). "In addition, Lcn-2 was shown to contribute to the polarization of macrophages and, in turn, to promote iron delivery to cancer cells, whereby the increase in intracellular iron protects cancer cells from apoptosis." (PMID 37958332, 2023). "However, the factors responsible for Lcn2 induction and its downstream effects are unknown, but LCN2 may contribute to cancer anorexia via its action on hypothalamic melanocortin signaling." (PMID 35031523, 2022).
cancer (continued). "However, the precise epigenetic mechanisms underlying the gene regulation of Lipocalin 2 (LCN2), SLC22A17, and MMP9 in cancer still remain unclear." (PMID 36211450, 2022). "Thus, the expression pattern and functional roles of LCN2 in cancer remain unclear and controversial." (PMID 35470375, 2022). "However, the role of LCN2 in the different processes of cancers is controversial." (PMID 36428800, 2022). "Taken together, these findings suggest that LCN2 could be a valuable biomarker for cancer cachexia." (PMID 36428623, 2022). "Thus, controversies over LCN2′s function remain in different cancer types." (PMID 34202288, 2021). "Based on the fact that expression profiles between HCC samples differ based on the cancer origin, it would be interesting to see whether LCN2 is a marker, which rises during NAFLD-induced HCC pathogenesis, and, if so, solely or as a part of a general modified gene profile." (PMID 33799862, 2021). "Thus, all these results suggested that LCN2 expression is elevated at the distant metastatic sites and may add prognostic value, particularly to Nottingham pathological grade and advanced cancer staging." (PMID 34072157, 2021). "However, the role of LCN2 in diverse cancers remains poorly defined." (PMID 33425761, 2020). "Hence, LCN2 has emerged as a potential therapeutic target against many cancer types." (PMID 32575507, 2020). "In sum, the role of LCN2 may be cancer-type specific and depend on iron saturation." (PMID 32328462, 2020). "After this very first allocation of LCN2 as a significant factor in guaranteeing immune balance, the repertoire of LCN2 functions was further expanded to many biological processes, including inflammation, intoxication, immune defense, organogenesis, and cancer." (PMID 27729871, 2016). "However, the specific functions of LCN2 and mechanisms underlying its modulation of cancer progression are not well characterized at present." (PMID 25940797, 2015). "However, Lcn2 plasma protein levels were elevated under both subacute and chronic inflammation, which may limit its usefulness as a cancer-specific biomarker." (PMID 21589862, 2011). "Our results imply that the observed upregulation of Lipocalin 2 in various types of cancer cells may be the direct consequence of concomitant UPR activation, and that the ER stress/Lipocalin 2 axis is a potential new target for intervention in cancer progression." (PMID 21649922, 2011). "Neutrophils also activate lipid carrier protein 2 (LCN2) secretion through enhanced STAT3 and induce mesenchymal–epithelial transition (MET) in cancer cells, acquiring an invasive phenotype, thereby promoting cancer cell colonization and metastasis." (PMID 40979214, 2025). "A similar trend was observed in circulating levels, with decreased LCN-2 and increased MMP-9 in cancer patients compared to healthy controls." (PMID 40214460, 2025). "Then, the top five higher binding energy ginsenosides were used for docking with other SLC transporters, including SLC7A5, SLC7A6, LCN2, and SLC7A9 cancer-related targets, as well as BSG due to its involvement in amino acid transport." (PMID 40566559, 2025). "H3K18 lactylation acts oncogenically by enhancing lipocalin 2 (LCN2) oncogene expression; inhibiting this mechanism can impede cancer metastasis." (PMID 41190507, 2025). "LCN2 stabilizes the proteolytic enzyme MMP-9, preventing auto-degradation and promoting the metastasis of cancer cells." (PMID 38673873, 2024). "LCN2 contributes to CRC progression by forming a complex with MMP9, an enzyme involved in degrading the extracellular matrix (ECM), thus enhancing cancer cell invasion and metastasis." (PMID 39839775, 2024). "After analyzing the top genes of this cluster, the top oncogenes LCN2 and SAA1 were found which were consistent with the findings of Chen’s work and both of them were confirmed to contribute to the progression of malignant tumors." (PMID 38880903, 2024).
cancer (continued). "Taken together, we propose a schematic model in which the LCN2/LOXL2/MMP9 complex promotes the migration and invasion of cancer cells through intracellular and extracellular means." (PMID 37753805, 2023). "First, we pretreated cancer cells with DMEM, DOX− 2nd CM, DOX+ 2nd CM, and DOX+ 2nd CM with recombinant LCN2, followed by mammosphere formation." (PMID 37174093, 2023). "Thus, the role of LCN2 in metastasis may differ significantly between different cancer types." (PMID 36926025, 2023). "Taken together, LCN2, LOXL2, and MMP9 are highly expressed in ESCC, and are emerging as promising therapeutic targets in many types of cancer." (PMID 37753805, 2023). "Meanwhile, our transcriptomic analysis demonstrated that conditioned media from c-Met high cells significantly induced the secretion of lipocalin 2 (LCN2) from neutrophils, which in turn promotes the self-renewal of cancer stem cells." (PMID 37174093, 2023). "To overcome this limitation, we recently tried to develop a novel cancer therapy, gene-interfered ferroptosis therapy (GIFT), by combining cancer cell-specific knockdown of two iron efflux genes, FPN and LCN2, with iron oxide nanoparticles (FeNPs)." (PMID 36329436, 2022). "The results of this study suggested that LCN2, SLC22A17, and MMP9 genes interact with each other, indicating their synergic involvement in cancer." (PMID 36211450, 2022). "Free light chains (FLCs), regulatory cytokines such as IL‐10, TGFβ, lipocalin‐2 (LCN‐2) and chemokines (e.g., CCCL1), promote cancer progression; however, CCCL5 chemokine has demonstrated an anticancer role." (PMID 35344301, 2022). "Subsequently, correlation analysis between the expression of LCN2, SLC22A17, and MMP9 genes and RPPA protein levels was performed to identify their involvement in cellular processes and cancer pathways." (PMID 36211450, 2022). "We further demonstrate that C/EBPB governs cancer stemness through the modulation of CLDN1 and LCN2." (PMID 35013251, 2022). "Recent studies have shown that lipocalin-2 (LCN2) has multiple functions involved in various biological and pathological processes including energy homeostasis, cancer, inflammation, and apoptosis." (PMID 34903175, 2021). "Subgroup-specific genes with strong effects on overall survival and high MIFs in the proposed weighted model involve the following cancer-related genes: ADH1C, BMP5, LCN2 and PLOD2 in GSE31210, CST1 in GSE37745, as well as AREG and COL4A3 in GSE29013." (PMID 34876106, 2021). "Two reports highlight a critical role of macrophage-secreted lipocalin-2 (LCN-2), a protein able to bind siderophore-complexed iron and to export it into the TME, in the promotion of cancer cells proliferation in vitro." (PMID 33540645, 2021). "Data support the use of high-molecular-weight matrix metalloproteinases (MMPs), such as the LCN2-MMP-9 complex, as independent predictors of metastatic phenotypes in several cancers, including prostate and bladder cancers." (PMID 32575507, 2020). "As vividly shown in the picture, LCN2 had strong physical interactions with MMP-9, which is crucial in cancer metastasis." (PMID 33425761, 2020). "Expression of lipocalin-2 and its receptor, SCL22A17, by cancer cells was essential for cancer cell growth at metastatic sites." (PMID 33679721, 2020). "In another study, lipocalin-2 was found to be predominantly expressed in TAM and to act as a paracrine factor that supplies iron, thus stimulating proliferation of cancer cells." (PMID 33679721, 2020). "Interestingly, MDA-MB-231 cells produce more lipocalin 2 (LCN2) protein compared to MCF-731, encoded by LCN2 that was downregulated in MDA-MB-231 but not MCF-7, further adding to the rationale as to why the eqMDEC secretome preferentially affects this cancer cell type." (PMID 33239740, 2020). "For example, LCN2, known to be overexpressed in human CRC and other cancers, is negatively correlated with Ruminococcaceae (Spearman rho = − 0.77, q value = 0.040), which is found depleted in CRC." (PMID 31992345, 2020).